TLR7 (toll like receptor 7)
Diseases named in the same sentence as TLR7 in open-access papers (continued):
Sharing a sentence is not in itself a finding about the gene and the disease.
autoimmune disease (continued). "Increases in TLR7 or TLR8 gene copy number can induce autoimmune disease in mice, and failures in X chromosome inactivation, where TLR7 and TLR8 are located, have been proposed as a cause of SLE in humans." (PMID 38780621, 2024). "Moreover, gene duplication of Tlr7, as seen in mice bearing the Y-linked autoimmune accelerator (Yaa) locus, contributed to accelerating autoimmune disease." (PMID 38791389, 2024). "TLR7 has been implicated in multiple autoimmune diseases including SS and T1D." (PMID 33322152, 2020). "Mutations within the TLR7 promoter increase autoimmune disease risk, especially in males." (PMID 30610201, 2020). "Notably, IRF7-mediated pathway of type I IFN responses is mainly initiated by ssRNA sensor TLR7, and previous studies reported that the over-expression or activation of TLR7 is associated with autoimmune diseases." (PMID 31603949, 2019). "Unlike other somatic cells, dynamic regulation of Xist RNA and heterochromatin marks on the inactive X (Xi) in female lymphocytes results in biallelic expression of some X-linked genes, including Tlr7, Cxcr3, and Cd40l, implicated in sex-biased autoimmune diseases." (PMID 30671059, 2018). "Thus, TLR7 responses are regulated during inflammatory disease conditions by release or overexpression of these molecules; for example, increased LL37 expression is associated with exacerbated TLR7-mediated cytokine production during autoimmune disease." (PMID 28928743, 2017). "The general predisposition of female individuals for developing autoimmune diseases was previously discussed in an animal model, demonstrating the higher rate of increased toll-like receptor 7-driven accumulation of CD11+ B lymphocytes in female than in male mice." (PMID 24516607, 2014). "Activation of B cells via TLR7 signaling has been implicated in the pathogenesis of autoimmune disease such as SLE, and Tlr7 deficient MRL/MpJ-Faslpr (MRL/lpr) mice do not produce anti-Smith (sm) antigen antibodies and show lessened immune activation and clinical disease." (PMID 25229618, 2014). "The answer likely lies in the fact that uncontrolled TLR7 signalling can cause autoimmune diseases." (PMID 23426937, 2013). "Additional work is necessary to determine the fate of biallelic Tlr7 B cells in autoimmune disease to reveal whether increased Tlr7 expression can impact loss of tolerance and if biallelic Tlr7 expressing cells undergo cell death to be removed from circulation." (PMID 41574968, 2026). "However, persistent TLR7 activation has been implicated in the pathogenesis of chronic inflammatory and autoimmune diseases, wherein it may contribute to sustained immune activation and tissue damage." (PMID 41012652, 2025). "In addition, TLR7 may be coexpressed with other X-linked genes (e.g., CXorf21) to jointly promote the occurrence of autoimmune diseases with gender bias." (PMID 36875095, 2023). "Enpatoran, also a TLR7/8 antagonist, exhibited moderate binding affinity, which correlates with its therapeutic potential in autoimmune diseases as reported in EMD Serono." (PMID 41231851, 2025). "Enpatoran with same similar TLR7/8 antagonist profile showed moderate binding affinity, correlating its potential in autoimmune disorder." (PMID 41231851, 2025). "This is demonstrated by the fact that knocking out either Tlr8 or Tlr9 in healthy C57BL/6 mice induced SLE-like autoimmune disease, while additional knockout of Tlr7 eliminated disease symptoms, indicating that the disease development was dependent on TLR7." (PMID 38791389, 2024). "An in-depth understanding of how to attain removal of self-reactivity in GCs while preventing Tlr7-driven self-reactive extrafollicular responses will be valuable in the fight against autoimmune diseases." (PMID 38866437, 2024). "Overall, there have been numerous studies investigating the role of TLR7 in skin wounds, inflammation, and development because of its significant role in various skin inflammations, allergies, autoimmune diseases and so on." (PMID 39153998, 2024).
autoimmune disease (continued). "Several immune genes (FOXP3, IL2RG, TLR7, TLR8, CD40LG, BTK, CXCR3) that are associated with increasing the likelihood of developing autoimmune disease in females are encoded on the X chromosome." (PMID 39286970, 2024). "Endosomal single-stranded RNA-sensing Toll-like receptor-7/8 (TLR7/8) plays a pivotal role in inflammation and immune responses and autoimmune diseases." (PMID 38589923, 2024). "Given that TLR7/9 activation has been implicated in the development and regulation of autoimmune diseases via anergy disruption and that hFcrl signaling increases TLR-mediated B cell activation, we investigated the effect of Fcrl5 on TLR7/9 signaling." (PMID 37841260, 2023). "TLR7 MyD88-dependant signaling pathway drives the production of type 1 IFN in human pDCs and is implicated in the pathogenesis of autoimmune diseases." (PMID 36677692, 2023). "Activation of TLR7 and TLR9 by recognition of self-nucleic acids is implicated in the pathogenesis and development of autoimmune disease." (PMID 37606045, 2023). "On the other hand, toll-like receptor 7 (TLR7), chromosome X open reading frame 21 (CXORF21), and CD40L are double expressed in women, determining an augmented risk of autoimmune diseases." (PMID 37511303, 2023). "This enhanced signaling in pSS pathology through TLR7/8, often triggered by viral entities, suggests that PRRs promote and influence the progression of autoimmune diseases by favoring a sustained inflammatory response." (PMID 36359340, 2022). "Antimalarial drugs, such as chloroquine (CQ), hydroxychloroquine sulfate (HQ), and quinacrine, serve as antagonists for TLR7, 8, and 9 and have been used for the treatment of autoimmune diseases, such as SLE and RA." (PMID 36359340, 2022). "The ligand–receptor interaction model proposed in the manuscript can be used as a benchmark for the development of a new generation of potent TLR7 antagonists of clinical significance in various autoimmune diseases." (PMID 35807273, 2022). "IFN‐α production via TLR7/9 in pDCs is activated via several signal pathways suggested to play an important role in several autoimmune diseases." (PMID 34270818, 2022). "Recently, new studies have focused on the involvement of several proteins in the TLR7 signaling pathways (e.g., TLR7 and MyD88), which have been identified as potential therapeutic targets for the treatment of autoimmune diseases." (PMID 33767707, 2021). "The importance of TLR signaling is well established in many autoimmune diseases, especially the implication of TLR7 in SLE both in humans and in mice." (PMID 34108972, 2021). "Heterozygous Unc93b1WT/PKP mice exhibit only mild signs of autoimmune disease and enhanced TLR7 signaling." (PMID 34440442, 2021). "The involvement of Toll-like Receptors (TLR) in the recognition of self-molecules is established for the RNA-sensing receptors of innate immunity, TLR7 and TLR8, which enhanced expression is directly linked to the pathogenesis of autoimmune diseases." (PMID 33498655, 2021). "Our work provides small-molecule TLR7-specific antagonists and suggests the TLR7-targeting strategy for treating autoimmune diseases." (PMID 33060576, 2020). "Since blocking of TLR7 is considered as a promising strategy for treating autoimmune diseases including SLE and psoriasis, there is an urgent need for the development of TLR7-specific antagonist." (PMID 33060576, 2020). "TLR7, an endosomal TLR, has been implicated in multiple autoimmune diseases including SS and type 1 diabetes (T1D)." (PMID 33322152, 2020). "Inhibition of endosomal TLRs, such as TLR-8 has great therapeutic potential for the treatment of autoimmune diseases as shown for the TLR7/8/9 antagonist chloroquine (CQN)." (PMID 32477333, 2020). "TLR7 activation in neutrophils also influences immune complex-mediated autoimmune diseases such as SLE, as it triggered the breakdown of FcγRIIA (CD32) located on pDCs and monocytes." (PMID 33297945, 2020).
autoimmune disease (continued). "TLR-8 specifically plays a role in autoimmune disorders because it is involved in the regulation of TLR-7 and TLR-9 signaling and a direct link has been found between the dysregulation of TLR-8 activation and pathological inflammation." (PMID 32477333, 2020). "This is consistent with observations of a prominent IFN-I signature in SLE and other autoimmune diseases, which was shown to further upregulate TLR7 and TLR9 expression, thereby potentially amplifying detrimental autoantibody production." (PMID 32547564, 2020). "Autoimmune disease in MRL-lpr mice is dependent on TLR7, TLR9, and toll-like receptor (TLR) signal transduction molecule Myeloid differentiation primary response 88 (MYD88)." (PMID 31824490, 2019). "Analysis of TLR7 at the protein level revealed that the expression in immune cells is dependent on the TLR7-transgene itself and/or autoimmune disease factors in a cell-specific manner." (PMID 31354711, 2019). "Although SLE is a complex autoimmune disease with extremely heterogeneous clinical manifestations as well as pathogenesis, TLR7 seems to play a pivotal role in the pathogenesis of SLE." (PMID 30210502, 2018). "The ability of TLR7/8 to recognise endogenously released RNA has implications for autoimmune diseases where TLR7/8 contributes to inflammation in RA and SLE." (PMID 29567473, 2018). "Stimulation through MYD88, TLR7, or TLR9 promotes autoimmune diseases, presumably by binding to RNA (TLR7), or DNA (TLR9) released from apoptotic cells." (PMID 29312329, 2017). "The possible role of TLR8 in autoimmune diseases has been recently considered, since together with TLR7 it is one of the two TLRs expressed on the X chromosome." (PMID 28245863, 2017). "Concurrently, the role of TLR7 in other autoimmune diseases has been widely reported, especially in the case of SLE." (PMID 26442097, 2015). "Similar to our results, a recently identified CD11b+CD11c+B220+CD21- B cell population was predominant in female aged and autoimmune disease-prone mice in response to TLR-7 signaling." (PMID 24472094, 2014). "Previous clues that TLR7 and TLR9 are handled differently by UNC93B1 came from experiments which showed that mice harbouring a mutant form of UNC93B1 succumbed to severe autoimmune disease due to enhanced TLR7 signalling and impaired TLR9 responses." (PMID 23426937, 2013). "Elevated levels of TLR7 have also been detected in autoimmune diseases mediated by autoreactive B-cell clones such as SLE and even in ITP." (PMID 21818370, 2011). "Thus, defective DCIR overstimulates autoreactive T cells by strengthening TLR7-mediated responses, thereby exacerbating TLR7-MyD88-mediated autoimmune diseases." (PMID 42256301, 2026). "Endosomal Toll-like receptors (TLRs, including TLR3, TLR7, TLR8 and TLR9) play crucial roles in immune responses by recognizing pathogen-associated molecular patterns; however, their aberrant activation is implicated in inflammatory and autoimmune diseases." (PMID 40887497, 2025). "Given the implication of TLR7 in autoimmune diseases, it is interesting to speculate that an attenuation of TLR7 signaling was necessary, leaving TLR8 to emerge as the primary miRNA-sensing TLR in humans." (PMID 41322409, 2025). "Despite being homologous proteins both expressed in B cells, studies in mice have showed that TLR7 and TLR9 manifest distinct regulation and have opposing roles in mouse models of autoimmune disease, with TLR7 promoting while TLR9 negatively regulating disease pathogenesis." (PMID 40904452, 2025). "In contrast, TLR7 and STING antagonists are promising to be applied to alleviate inflammation, improve the severity of inflammation, reduce cytokine storms caused by viral infections, and treat autoimmune diseases." (PMID 41516215, 2025). "Hence, patients with TLR7 LOF variants exhibit IFN-mediated innate immunodeficiency whereas patients with TLR7 GOF variants are predisposed to neuroinflammation and/or autoimmune diseases." (PMID 40423910, 2025).
autoimmune disease (continued). "Consequently, the development of selective TLR7/8/9 inhibitors has become a focal point of research, with several compounds currently undergoing clinical trials for the treatment of autoimmune diseases." (PMID 40640149, 2025). "If TLR8 regulates TLR7 expression upstream of TLR7 in humans, the association of TLR8 with autoimmune disease pathogenesis may have been underestimated and should be investigated." (PMID 39544932, 2024). "The most notable feature of X-linked genes affected by Xist perturbation is the high number of genes involved in innate immune response (TLR7, TLR8, TLR13, TASL, and CXCR3), which have been reported to be associated with or to have a causative role in different autoimmune diseases." (PMID 38701219, 2024). "Accordingly, these data suggest TLR7 activation also exacerbates HFD‐induced dysregulation of glucose handling FVB/N mice, supporting the possibility that endogenous TLR7 activation may contribute to dysglycemia in patients with autoimmune disease." (PMID 38346802, 2024). "Recent studies suggest that exosome-derived miR-574-5p might play important roles in immune and inflammation responses, autoimmune diseases and cancer through activating TLR7/8." (PMID 38589923, 2024). "Furthermore, recent advancements in the development of dual TLR7/9 antagonists have opened new avenues for therapeutic applications in autoimmune diseases due to their selective inhibition properties." (PMID 38732254, 2024). "The identification of patients with coding variants in TLR7 and TLR8 has established the relevance of dysregulation of these receptors for human autoimmune disease, but equivalent coding variants in UNC93B1 that alter TLR responses to self-nucleic acids have not yet been described." (PMID 38780621, 2024). "Our study contributes to a growing body of literature supporting the possibility that endogenous TLR7 activation may contribute to dysglycemia in the setting of obesity and perhaps in patients with autoimmune disease." (PMID 38346802, 2024). "To investigate whether upregulated Fcrl5 expression affects autoimmune disease progression, we used the TLR7 agonist imiquimod-induced SLE-like model." (PMID 37841260, 2023). "However, Tlr7-null and Tlr7/9 double-null autoimmune disease-prone mice exhibit less severe disease." (PMID 36875095, 2023). "In many other contexts, female sex is associated with a stronger antibody response and also greater susceptibility to autoimmune diseases such as SLE, partly due to higher expression of X-linked immune genes such as TLR7 and higher type-1 interferon production." (PMID 36669118, 2023). "Based on its importance in other autoimmune diseases, we hypothesized that TLR7 activation accelerates pSS pathogenesis." (PMID 36591307, 2022). "TLR7 was found to be significantly increased in some autoimmune diseases, including SLE and pSS." (PMID 33767707, 2021). "In contrast, deletion of TLR7 signaling attenuates autoimmune disease progression." (PMID 30610201, 2020). "Since the pristane model is TLR7-dependent, it is likely that BALB/c mice have a genetic susceptibility to TLR7 induced autoimmune disease that is not present in B6 mice." (PMID 31998321, 2019). "For example, IRS 954 (a TLR7/TLR9 inhibitor) has been reported to have a potential in reducing pathogenesis of autoantibody production and autoimmune tissue injury in SLE, another autoimmune disease associated with EBV." (PMID 29995930, 2018). "The PBD carries a significant segment, the PBM, that could serve as a decoy to prevent or dissociate TIRAP from the membrane in order to control dysregulated and overexpressed TLR2/TLR4/TLR7/TLR9-dependent autoimmune diseases." (PMID 29434596, 2018).
autoimmune disease (continued). "It is thus hypothesised that in some autoimmune diseases deficiency of either TLR8 or TLR9 will result in decreased competition of these endosomal TLRs to bind to Unc93B1, making TLR7 more available and resulting in higher TLR7 trafficking and response." (PMID 28553556, 2017). "Thus, TLR7 and TLR9 have opposing pathogenic and protective roles, respectively, in autoimmune disease." (PMID 28751890, 2017). "Illness may be caused by constitutive activation of human TLR7 or TLR8 in the bacterial artificial chromosome positive mice as increased TLR7 and TLR8 expression or activation has previously been implicated in autoimmune disease." (PMID 25229618, 2014). "The culture system used in this study also demonstrates that in an antigen-independent environment locally overexpressed IL-7 and TLR7, as has been shown in several autoimmune diseases, are sufficient to trigger immunoglobulin production, which makes this a relevant observation." (PMID 24740301, 2014). "Although these results point to an important role for TLR7 and 9 in SLE development, it is important to note that mice deficient in TLR7/9 as well as MyD88 are not free of autoimmune disease symptoms." (PMID 23936008, 2013). "Consequently, the possible therapeutic use of TYK2 inhibitors in autoimmune diseases should take into account their impact on TLR7 expression, which may lead to a low antiviral response in these patients." (PMID 38683377, 2024). "Furthermore, regulation of the cytokine expression induced by TLR7 agonists may be beneficial in reducing the exacerbation of certain types of autoimmune diseases, including SLE." (PMID 38077311, 2023). "Both TLR8 and TLR7 could contribute to the pathogenesis of autoimmune diseases." (PMID 33498655, 2021). "The formation of spontaneous germinal centers (Spt-GCs), whose dysregulation is associated with SLE and other autoimmune diseases, was shown to be dependent on MAVS and TLR7 expression in mice, and TLR7 ligation could only partially reinstate the Spt-GC development." (PMID 32547564, 2020). "We used mice that were double-knockouts for TLR7 and TLR8 (TLR7/8 KO) to test the hypothesis that a dual antagonist of these receptors could protect from PD degeneration seen as autoimmunity disease, reducing the production of lymphocytes directed against DA neurons." (PMID 33317145, 2020). "It is also not clear whether significantly reduced B10 cells caused by TLR7 overactivity play any role in promoting SLE-like autoimmune disease in these mice." (PMID 32849556, 2020). "Thus, we propose that the mechanism we have identified involving increased expression of CXorf21 in female immune cells that affects TLR7 signaling and interferon will be operative in autoimmune diseases in which the pathogenesis involves TLR7 signaling and an interferon signature." (PMID 31695690, 2019). "Considering that TLRs, including TLR7, -8, and -9, are also implicated in autoimmune diseases, these TLRs may also contribute to EBV-associated autoimmune diseases, since EBV is able to regulate their expression and may have some other interactions with signaling pathways mediated by these TLRs." (PMID 21429244, 2011). "We did not study the other functions of R848 and TLR7/8, such as R848’s immuno-stimulation and antiviral properties through TLR7/8, or TRL7/8’s involvement in autoimmune disease inhibition, antiviral, and antitumor effects." (PMID 40917886, 2025). "Toll-like receptor 7 (TLR7) and Stimulator of Interferon Genes (STING) ligands possess a series of immunomodulatory effects such as anti-infection, anti-tumor, and autoimmune-disease-alleviating effects." (PMID 41516215, 2025). "TLR7 and TLR8 have gained significant attention due to their role as potential therapeutic targets in autoimmune diseases, vaccination adjuvants and targeted immunotherapy in cancer." (PMID 41322409, 2025).